APOE (apolipoprotein E)
Diseases named in the same sentence as APOE in open-access papers (continued):
Sharing a sentence is not in itself a finding about the gene and the disease.
atherosclerosis (continued). "Although the role of APOE in cholesterol homeostasis and its regulatory mechanism in atherosclerosis and Alzheimerʼs disease (AD) are well known, the role and mechanism of APOE in cancer remains elusive." (PMID 35090515, 2022). "Secondly, in diabetic ApoE KO mice, where activation of the renin angiotensin system drives accelerated atherosclerosis, rmACE219-613 also reduced plaque accumulation in the aorta after 6 weeks." (PMID 35624851, 2022). "ApoE knockout (KO) mice, the most popular animal model for human atherosclerosis, were fed a Western diet and injected with adenovirus (Ad) C1QL1 or Ad green fluorescent protein (GFP) through the tail vein for 12 weeks to confirm this assumption." (PMID 36286293, 2022). "After showing that L. saccharolyticum effectively converted choline to TMA by in vitro incubation, we then investigated the possible implication of L. saccharolyticum in atherosclerosis in ApoE−/− mice." (PMID 35273169, 2022). "An additional group of A2Kb-Tg ApoE–/– mice were then immunized with MSA-PAM to determine if amphiphilic micelles with a different self-peptide would affect atherosclerosis in the humanized mouse model." (PMID 35536648, 2022). "In this study, ApoE−/− mice were fed a continuous high-fat diet combined with binding stimulation, and an animal model of atherosclerosis co-depression was established based on the “microbiota-gut-brain axis” theory." (PMID 35558553, 2022). "ApoE-knockout mice are more likely to develop atherosclerosis due to an accumulation of unprocessed lipids with difficulties in the endocytosis of IDL triglycerides." (PMID 35269673, 2022). "Mice that lack genes involved in the clearance of LDL from the bloodstream, such as the LDL receptor and apolipoprotein E, are widely used models of experimental atherosclerosis." (PMID 36714321, 2022). "Conversely, CD11c+CD44+ macrophages significantly increased with atherosclerosis from 3.8 ± 0.4% in WT to 26.3 ± 2.1% in ApoE−/− (HFD) mice." (PMID 35017526, 2022). "We tested if the PAM nanoparticle platform can function as a vaccine formulation to reduce atherosclerosis in hypercholesterolemic ApoE–/– mice and explored its potential mechanisms of achieving such an effect." (PMID 35536648, 2022). "We found that ApoE−/−;SAP−/− mice were obviously separated from ApoE−/− mice and tended to approach C57 mice, which showed that SAP deficiency can improve the metabolic disorders caused by atherosclerosis, to a certain extent." (PMID 36557316, 2022). "For atherosclerosis, a western diet was used to feed the ApoE−/− mice for 12 weeks to establish the classical atherosclerosis mouse model as we previously reported and the entire aortas were harvested for analysis." (PMID 36585926, 2022). "After validating using Gene Expression Omnibus (GEO) datasets and the atherosclerosis and MI mice model, eight proteins were validated using ApoE-/- and C57 mice." (PMID 35845072, 2022). "Regarding the protective role of these metabolites against atherosclerosis and on bone mineralization, a similar procedure should be applied in ApoE KO mice with reduced kidney function." (PMID 36009040, 2022). "Though MAC is traditionally believed to have a role in microbial infections, complement‐induced MAC is crucial in the progression of atherosclerosis in ApoE knockout mice." (PMID 35141476, 2022). "There it was demonstrated that TRAF6 stop 6877002 treatment in ApoE−/− mice reduces existing atherosclerosis by decreased macrophage activation and leukocyte recruitment." (PMID 36267276, 2022). "In another study, treatment with Lactobacillus acidophilus ATCC-4356 reduced the burden of atherosclerosis in apolipoprotein e (ApoE)−/− mice." (PMID 35370631, 2022). "Potential clinical relevance of P210-PAM immunization was demonstrated by reduced atherosclerosis in the humanized ApoE–/– mouse model." (PMID 35536648, 2022). "We have also studied crossbreds of thalassemic high RDW mice with atherosclerosis-prone ApoE−/− strain." (PMID 35953533, 2022).
atherosclerosis (continued). "In the present study, the plasma proteomic changes of atherosclerosis in ApoE knockout mice after exercise were analyzed by LC-MS/MS." (PMID 35205118, 2022). "The humanized targeted APOE mouse model (TR-APOE) was developed by introducing the human APOE gene to replace the murine APOE gene to study the APOE genotype effects on atherosclerosis." (PMID 36077227, 2022). "PLAU has also been reported to be associated with atherosclerosis plaque formation and AMI: macrophage–specific overexpression of the PLAU gene accelerated atherosclerosis, coronary artery occlusions, and premature death in ApoE−/− mice." (PMID 35795669, 2022). "Increased circulating corticosterone levels have been shown to accelerate dyslipidaemia and atherosclerosis, in parallel with cognitive decline in ApoE-/- mice." (PMID 36104381, 2022). "There are three isoforms for ApoE, ApoE2‐4, from which ApoE4 is associated with higher serum levels of triglycerides and LDL‐C contributing to atherosclerosis." (PMID 35411714, 2022). "The consequence of the reduced renal function induced by adenine on atherosclerosis development was evaluated by quantifying atherosclerotic plaque in aortic valve sections of ApoE KO mice 5 weeks after starting with adenine." (PMID 36009040, 2022). "In a previous study conducted in apolipoprotein E-deficient mice, ablation of the A-FABP gene provided dramatic protection against atherosclerosis in the settings of early and advanced atherosclerosis." (PMID 35448081, 2022). "Animal experiments using apolipoprotein E-deficient mice have shown that ONO-5430514 attenuates endothelial dysfunction and prevents atherosclerosis, making it a target for the treatment of atherosclerosis." (PMID 36547431, 2022). "Deficiency or suppression of all three acute phase SAAs: SAA1, SAA2.1, and SAA3 was necessary to significantly reduce atherosclerosis in apoE−/− mice." (PMID 36297390, 2022). "Based on the “microbiota-gut-brain axis,” this study aimed to investigate the changes of lipid metabolites in the prefrontal cortex and hippocampus regions and the characteristics of the gut microbiota in ApoE−/− mice with atherosclerosis co-depression." (PMID 35558553, 2022). "More importantly, BMP4 deficiency in adipose tissues exacerbates atherosclerosis, while BMP4 overexpression in adipose tissues promotes PVAT browning and atheroprevention in ApoE-/- mice." (PMID 36172381, 2022). "EC-targeted Trx2+/+ mice show increased scavenging activity for H2O2 and O2•−, ApoE−/−/Trx2+/+ mice show improved EC function and reduced atherosclerosis and mice with targeted cardiac Trx2−/− exhibit high oxidative status and vascular lesions." (PMID 35883899, 2022). "In spite of this, ApoE−/−MHCII−/− mice had significantly more atherosclerosis due to losing regulatory T cells." (PMID 35056557, 2022). "The results suggest that the possible reason for GPE attenuating atherosclerotic lesions significantly and delaying the progression of atherosclerosis is the effect of GPE on the gut microbiota of ApoE−/− mice." (PMID 36145277, 2022). "IFNγ-B cells show the genetic makeup of GC B cells with increased expression of PD-L1 and TGF-β and effectively inhibit TFH cells in vitro and in vivo and ameliorate atherosclerosis development in apoE−/− mice." (PMID 35187121, 2022). "Circulating hMSCs attach to athero-prone endothelium more frequently in an ApoE animal model of atherosclerosis." (PMID 36430208, 2022). "Since body weight, plasma lipid levels, and glucose levels are associated with atherosclerosis development, we measured body weight, plasma lipid levels, and glucose levels in SRC-3-/-ApoE-/- and SRC-3+/+ApoE-/- mice after the mice were fed a WD for 12 weeks." (PMID 36263184, 2022). "By administering GSK’547, we aimed to evaluate the drugability of RIPK1 kinase in ApoE−/− Fbn1C1039G+/− mice, which is a unique model of advanced human-like atherosclerosis." (PMID 35625752, 2022).
atherosclerosis (continued). "Inhibiting IL-6/STAT3 signaling pathway can protect against high-fat-induced atherosclerosis in ApoE (-/-) mice." (PMID 35783840, 2022). "TRX1 expression is therefore linked to atherosclerosis and reduces lesion formation via NLRP3 inflammasome inhibition in ApoE−/− mice." (PMID 36497101, 2022). "Overt atherosclerosis can be observed as plaques that are visible by histology in some mouse models such as apolipoprotein E (ApoE) knockouts." (PMID 35419427, 2022). "Of note, a critical role of the endothelial NF-κB pathway was evidenced in animal models of atherosclerosis, where genetic abrogation of the signaling prevented the development of atheroma lesions in Western-diet-fed apolipoprotein E knock-out (ApoE−/−) mice." (PMID 36286429, 2022). "The potential implications of these results remain to be elucidated; however, the decreased TC and LDL indicated an anti-atherosclerosis effect of HFD-LI in ApoE KO mice." (PMID 36555552, 2022). "Methods and Results: Our data showed that sclerostin suppressed inflammatory responses, prevented aortic aneurysm (AA) and atherosclerosis progression in hSOSTki.Col1a2+/G610C.ApoE-/- mice." (PMID 35966595, 2022). "The symptoms observed in ApoE/NOS3−/− mice are caused by the loss of function of the ApoE and NOS3 genes, and the etiology of hypertension and atherosclerosis is often complicated and unclear in clinical practice." (PMID 36360235, 2022). "For example, when PAPPA, the protease of IGFBP4, was genetically overexpressed in atherosclerosis models (APOE-KO), IGF bioavailability was enhanced due to reduced IGFBP4, resulting in a more severe atherosclerotic plaque formation." (PMID 36351970, 2022). "In low shear stress areas created in ApoE knockout mice, atherosclerosis develops rapidly, so if immature smooth muscle cells play any role in atherogenesis, they should appear there." (PMID 35163667, 2022). "To evaluate the effect of F. nucleatum on the cardiovascular system, we established atherosclerosis models by using ApoE–/– mice." (PMID 35359716, 2022). "Our results revealed that inducible deletion of NEMO in SMCs significantly inhibited HFD-induced atherosclerosis in ApoE−/− mice." (PMID 35869246, 2022). "To investigate the effects of miR-185-5p on atherosclerosis, we fed a high-fat diet to apoE-/- mice to induce atherosclerosis." (PMID 35172278, 2022). "It showed that Dnmt3b silencing attenuated atherosclerosis, including decreased lesion size and macrophage content and increased collagen and smooth muscle cells content in ApoE−/− mice." (PMID 35422896, 2022). "Earlier, in a mouse model of atherosclerosis, ApoE−/− mice fed a Western diet (high fat and high cholesterol diet) increased blood levels of LacCer, which was correlated with increased arterial stiffness, and aortic media–intima media thickening (AOIMT)." (PMID 36499769, 2022). "In apoE knockout mice, the addition of butyrate in the diet reduces atherosclerosis and lowers the secretion of inflammatory cytokines." (PMID 35498045, 2022). "The HNF4A network is composed of 35 target genes, including activation of APOE which contributes to altered VLDL metabolism and increased atherosclerosis susceptibility in NAFLD." (PMID 35925965, 2022). "We then investigated the use of P210 in self-assembling peptide amphiphile micelles (P210-PAMs) as a vaccine formulation to reduce atherosclerosis in B6.129P2-Apoetm1Unc/J (ApoE–/–) mice and P210’s potential mechanisms of action." (PMID 35536648, 2022). "Meanwhile, SnPP, as a HO-1 inhibitor, persistently and exclusively increased the NK cells in both the spleen and peripheral blood, and exacerbated atherosclerotic lesion in ApoE-/- mice, further highlighting the contribution of NK cells to atherosclerosis." (PMID 35281895, 2022).
atherosclerosis (continued). "The group found that as atherosclerosis developed in the ApoE null mice, their gut bacterial composition changed." (PMID 35056557, 2022). "APOE is well-known for its protective role in atherosclerosis, and APOE-knockout (KO) mouse model is often used as pre-clinical atherosclerosis model." (PMID 36351970, 2022). "AKT1 is the center of the PI3K-AKt signaling pathway, and inhibition of its overactivation can alleviate high-fatdiet-induced atherosclerosis in ApoE + mice." (PMID 36212940, 2022). "Dominant-negative Clock mutant apolipoprotein E (Apoe)-/- mice reveal increased atherosclerosis by enhancing intestinal cholesterol absorption, promoting modified lipoprotein uptake, and decreasing cholesterol efflux from macrophages." (PMID 35111358, 2022). "A reigning notion is that the plasmalogens act to protect lipoproteins, amongst others, from oxidation and that increasing plasmalogens on lipoproteins can attenuate atherosclerosis in ApoE-null mice." (PMID 36592658, 2022). "In ApoE–/– mice, the development of atherosclerosis is spontaneous, even when fed a normal chow-diet." (PMID 35845572, 2022). "PON1−/− mice show increased aortic O2•− and leukocyte adhesion; conversely, ApoE−/−/PON1+/+ mice show reduced atherosclerosis." (PMID 35883899, 2022). "To investigate the effect of NETs on atherosclerosis in vivo, we generated neutrophil-specific Pad4 knockout mice (ApoE−/−; Neu-Pad4−/−) by crossing Pad4fl/fl mice with Tg-Mrp8-Cre mice and then crossing them with an ApoE−/−mice." (PMID 35923856, 2022). "The reference with the strongest burst (8.06) demonstrated that IL-37 protects against the development of atherosclerosis in ApoE-/- mice by eliminating the maturation of DCs." (PMID 35935954, 2022). "Exogenous administration of fingolimod decreased the development of atherosclerosis in LDL receptor-deficient mice and ApoE-deficient mice." (PMID 36119733, 2022). "In summary, an adequate intake of DP was able to counteract atherosclerosis development in ApoE−/− mice, and this study provides a scientific theoretical basis for the application of DP in the food and pharmaceutical fields." (PMID 35215505, 2022). "The complete cav1 knockout also inhibits atherosclerosis in apoE−/− mice fed a high-fat diet and endothelial LDL transcytosis in vitro." (PMID 35464770, 2022). "We have previously found that dietary iron overload mitigates atherosclerosis in high-fat diet (HFD)-fed apolipoprotein E knockout (ApoE-KO) mice by impairing hepatic fatty acid metabolism." (PMID 35956917, 2022). "Accordingly, in the present work, we chose the KKAy+/– mice backcrossed for six generations with ApoE–/– to generate a mouse model of combined MetS and atherosclerosis." (PMID 36505365, 2022). "In a humanized atherosclerosis model (ApoE*3Leiden transgenic mice), quercetin significantly attenuated atherosclerosis." (PMID 35120520, 2022). "This was explained by the fact that in the mouse model used (ApoE−/−), IL-1α mostly contributes to the development of atherosclerosis." (PMID 32648087, 2021). "Thus, the plaque areas were increased in apoE-/-mice fed a flavonoid-deficient diet, despite the fat levels of these diets being very low (4%), suggesting that quercetin-like plant flavonoids protect against the development of atherosclerosis as cofactors of COX-2." (PMID 34592918, 2021). "The results demonstrated that treatment with rSj-Cys significantly reduced body weight gain, hyperlipidemia, and atherosclerosis induced by the high-fat diet in apoE–/– mice." (PMID 34901005, 2021). "Recently, IL-38 overexpression was found to inhibit hyperlipidemia and atherosclerosis in apoE−/− by alleviating inflammation." (PMID 34388961, 2021).
atherosclerosis (continued). "An experimental study on mice found that berberine slows down the progression of atherosclerosis in apolipoprotein E knockout (ApoE-/-) cholesterol-fed mice." (PMID 34351937, 2021). "IFNγ administration exacerbated AS via increasing the T-cell number within lesions in atherosclerosis-prone apoE-/- mice." (PMID 34658858, 2021). "Berberine intake was indicated to elevate intestinal Akkermansia levels and reduce atherosclerosis in ApoE -/- mice on high-fat diets." (PMID 34576810, 2021). "In our study, LAMP-2A (L2A, a CMA marker) was reduced in macrophages exposed to high dose of oleate, and lipophagy was impaired in advanced atherosclerosis in ApoE (−/−) mice." (PMID 32285315, 2021). "The specificity and sensitivity of 5HFeC NPs were evaluated using magnetic particle imaging (MPI), fluorescence imaging (FLI), and computed tomographic angiography (CTA) in an ApoE-/- atherosclerosis mouse model." (PMID 33391489, 2021). "In summary, this study proves that agmatine inhibits the progression of atherosclerosis and attenuates hepatic steatosis by reducing the levels of triglyceride in the serum and in the liver of apoE−/− mice on a Western high-fat diet." (PMID 34639029, 2021). "ApoE−/− mice were fed with a “western diet” for 2 months to establish an early atherosclerosis model." (PMID 33462182, 2021). "In ApoE−/−Fas−/− double knockout mice, which display a lupus profile with accelerated atherosclerosis, resveratrol was able to prevent atherosclerosis progression." (PMID 34771008, 2021). "Other experimental studies described the development of atherosclerosis with severe pulmonary arterial hypertension in apoE-/- mice feeding high fat diet." (PMID 34816004, 2021). "Endothelial-specific P2Y2R deletion prevents atherosclerosis in apolipoprotein E null (ApoE−/−) mice." (PMID 34943862, 2021). "For this purpose, we employed monocyte adhesion to human umbilical vein endothelial cells (HUVECs) and HFD-induced atherosclerosis development in ApoE knockout (KO) mice along with O-1602 as a GPR55 agonist and CID16020046 as a specific GPR55 antagonist." (PMID 34884889, 2021). "Overexpression of MT1-MMP increased whereas knockdown of MT1-MMP expression ameliorated the development of atherosclerosis in a well-established mouse model of atherosclerosis, apolipoprotein E knockout (apoE−/−) mice." (PMID 34297054, 2021). "Contrast agent-enhanced microCT can overcome this issue, whereby visualization of atherosclerosis in ApoE−/− mice with microCT has been achieved with phosphotungstic acid (PTA)." (PMID 34594369, 2021). "For instance, the upregulation of miR155 increases the atherosclerosis lesion size, cell apoptosis, total triglyceride and cholesterol levels by inhibiting Bmal1 expression in ApoE−/− mice." (PMID 34575881, 2021). "It is well-known that ApoE−/− mice is used to reduplicate the atherosclerosis model, and the vascular endothelial cell injury model is mostly HUVECs induced by ox-LDL or H2O2." (PMID 34305600, 2021). "In a mouse model of advanced atherosclerosis, we previously found active neuroinflammation in CP and periventricular areas in aged ApoE-/- mice under high-fat diet." (PMID 33937770, 2021). "By contrast, the genetic deletion of IL-1β and IL-18 significantly reduced the development of atherosclerosis in ApoE-/- mice." (PMID 34094640, 2021). "We found that compared with the ApoE–/– mice treated with H. pylori-derived-OMVs, there were less atherosclerosis plaque formation in ApoE–/– mice treated with LPS-depleted OMVs or OMVs originated from CagA-negative bacterial strain." (PMID 34790655, 2021). "To characterize the role of B cells and antibodies in atherosclerosis, we generated ApoE-/- Aid-/- mice which develop hypercholesterolemia and are deficient in generating class-switched antibodies." (PMID 34305930, 2021).